ARF6 (ARF GTPase 6)
Diseases named in the same sentence as ARF6 in open-access papers (continued):
Sharing a sentence is not in itself a finding about the gene and the disease.
breast carcinoma (continued). "Furthermore, ARF6 silencing impairs invasion of breast cancer, melanoma and glioma, providing evidence that ARF6 is an important driver of cancer cell invasion and metastasis." (PMID 32426352, 2020). "Moreover, a direct correlation between ARF6 protein expression levels and breast cancer cell invasiveness was shown in breast cancer cell lines with different invasive abilities." (PMID 32426352, 2020). "The MMTV-PyMT mouse model might also be useful to study the immune-based therapies against the Arf6-overexpressing breast cancer cells." (PMID 29329590, 2018). "It is noteworthy that Arf6 expressed in breast cancer cells is required for cancer metastasis." (PMID 28900118, 2017). "Moreover, similarly to that in breast cancer cells, Arf6 and EPB41L5 were found to accumulate at the invadopodia of LPA-stimulated 786-O cells." (PMID 26854204, 2016). "Our results demonstrated that the ZEB1-EPB41L5 axis is at the core of the cancer mesenchymal program that drives ARF6-based invasion, metastasis and drug resistance of significant populations of primary breast cancers, and is tightly correlated with the poor outcomes of patients." (PMID 27617643, 2016). "Arf6 also regulates the cell motility of MDA-MB231 breast cancer cells through the recycling of integrin β to the cell surface, suggesting the importance of the Arf6-mediated polarized transport of cell adhesion molecules, such as cadherin and integrin, during cell migration and cancer invasion." (PMID 27622210, 2016). "The expression of both ARF1 and ARF6 is up-regulated in the most invasive breast cancer cell lines." (PMID 26908458, 2016). "Our results indicate that Arf6 plays an important role in the regulation of E-cadherin internalization in response to EGF, and suggest that Arf6 may exert its function by physically interacting with E-cadherin in breast cancer." (PMID 25678857, 2015). "Therefore, our results suggest that Arf6 activation serves as a mediator of EGF-stimulated E-cadherin internalization in breast cancer cell." (PMID 25678857, 2015). "Recent studies including the results from our laboratory showed that EGF treatment also could induce Arf6 activation and increased breast cancer cell migratory potential." (PMID 25678857, 2015). "Indeed, analysis of several breast cancer cell lines of differing metastatic capacity showed a direct correlation between ARF6 protein expression and their invasive potential." (PMID 26185744, 2015). "Arf6 may function on its GTP-bounded status to promote EGF-stimulated E-cadherin internalization in breast cancer cells." (PMID 25678857, 2015). "Because EGFR signaling activates ARF6 and induces breast cancer invasion, we tested whether impaired EGFR signaling could reproduce the intrahepatic biliary defects observed in arf6-ATG MO-injected larvae." (PMID 26379158, 2015). "Moreover, FBX8 inhibits ARF6-mediated cell invasion activity in breast cancer and c-Myc stimulates cell invasion by inhibiting FBX8 function." (PMID 23826080, 2013). "Since it is known that GEP100 regulates the endocytosis of β1-integrin, Arf6-mediated trafficking of β1-integrin may contribute to the acquisition of invasive phenotypes in breast cancer cells." (PMID 22605996, 2012). "Interestingly, Arf6 is localized to invadopodia and is crucial for invasion of breast cancer and melanoma cells and sustained activity of Arf6 enhances the invasive capacity of both of these cell types." (PMID 23056266, 2012). "We have shown that the Arf6 protein is overexpressed in all of the highly invasive breast cancer cell lines we examined, to levels 10- to 20-fold higher than those observed in noninvasive breast cancer cell lines as well as human normal mammary epithelial cells (HMECs)." (PMID 19416474, 2009). "Interestingly, we found that the MVP is crucial for ARF6 activation in breast cancer cells." (PMID 36408139, 2022).
breast carcinoma (continued). "Given the common usage of protein tyrosine phosphorylation, as well as the frequent use of these animal models for studying breast cancer at the molecular level, we here investigated whether mammary tumors in these mouse models utilize the Arf6-based pathway for invasion." (PMID 29329590, 2018). "Moreover, FBX8 over-expression could inhibit ARF6-mediated cell invasion activity in breast cancer cells." (PMID 23826080, 2013). "Besides breast cancers, melanomas also utilize Arf6 activity for their invasion and metastasis." (PMID 21966491, 2011). "The overexpression of components of the ARF6-based mesenchymal pathway and enhanced MVP activity also correlated with poor prognosis in breast cancer patients." (PMID 37834383, 2023). "It is reported that ARF6/ERK/uPAR signaling pathway boosts the cancer cell invasion and metastasis in breast cancer." (PMID 37716993, 2023). "In breast cancers, GEF100, another GEF protein of ARF6, has been shown to bind Tyr1068/1086-phosphorylated EGFR to activate Arf6 to induce TNBC invasion and metastasis." (PMID 36224181, 2022). "A molecular cascade consisting of the Arf-GEF GEP100, Arf6 and the Arf-GAP AMAP1 promotes tumor invasion and metastasis in breast cancer in response to EGF receptor activation." (PMID 33673086, 2021). "In particular, cancer-derived MVs are enriched in ADP-ribosylation factor 6 (ARF6), which promotes MVs shedding from plasma membrane of prostate and breast cancer cell lines." (PMID 31281356, 2019). "ADP-ribosylation factor 6- (ARF6-) mediated invasion and cytoskeletal remodeling in prostate and breast cancers are accused of the shedding MVs and all other classes of EVs." (PMID 31428232, 2019). "The study highlights a potential role for ARF6 in linking EGF-receptor signaling to Rac1 recruitment and activation at the plasma membrane to promote breast cancer cell directed migration." (PMID 28524754, 2019). "Arf6 and its downstream effector AMAP1 are often overexpressed in breast cancer cells, and promote invasion, metastasis, and drug resistance." (PMID 29329590, 2018). "ARF6 and its effector AMAP1 are often overexpressed in different types of cancers, such as breast cancer and renal cancer, and in these cancers, AMAP1 binds to EPB41L5 to promote invasion, metastasis, and drug resistance." (PMID 27871329, 2016). "We previously showed that the small GTPase ARF6 and its effector AMAP1 are often overexpressed in different types of cancers, including breast cancer and renal cancer, and play pivotal roles in promoting invasion, metastasis, and drug resistance." (PMID 27871329, 2016). "ARF6 and its effector AMAP1 are frequently overexpressed in breast cancer cells, and promote invasion, metastasis and drug resistance." (PMID 27617643, 2016). "Cancer-derived MV are enriched in the ADP-ribosylation factor 6 (ARF6), which functions as a promoter of EV shedding from prostate and breast cancer cell lines." (PMID 26861306, 2016). "By contrast, GEP100, a GEF for Arf6, links EGFR signaling to Arf6 activation to induce invasive activities of breast cancer cells." (PMID 25678857, 2015). "Our data suggest a role for ARF6 in linking EGF-receptor signaling to Rac1 recruitment and activation at the plasma membrane to promote breast cancer cell directed migration." (PMID 25799492, 2015). "In fact, it is reported that GEP100, a GEF for Arf6, links EGF/EGFR signaling to Arf6 activation to induce invasive activities of breast cancer cells." (PMID 25779663, 2015).
breast carcinoma (continued). "We have observed that siRNA-mediated knockdown of GEP100, Arf6 and AMAP1 greatly enhances sensitivity to ionizing-radiation of MDA-MB-231 breast cancer cells (our unpublished results), in addition to the blockage of invasive and metastatic activities." (PMID 24116160, 2013). "Arf6 and its effector, AMAP1, are frequently overexpressed in breast cancer, and constitute a central pathway to induce the invasion and metastasis." (PMID 21858086, 2011). "Both Arf6 and AMAP1 are also expressed at high levels in endothelial cells, as seen with highly invasive breast cancer cells." (PMID 21858086, 2011). "HUVECs are known to express Arf6 at a high level, which we found to be almost equivalent to that observed with highly invasive MDA-MB-231 breast cancer cells." (PMID 21858086, 2011). "siRNA-mediated knockdown of GEP100, Arf6 and AMAP1 each effectively inhibits the invasive activities of breast cancer cells." (PMID 19416474, 2009). "We have shown that Arf6 and its effector AMAP1 (DDEF1, DEF1, ASAP1 and centaurin β4) are abnormally overexpressed in some breast cancers and used for their invasion and metastasis." (PMID 19416474, 2009). "Like Arf6, AMAP1 is also abnormally overexpressed (> 10 fold) in highly invasive breast cancer cell lines, as compared with weakly- and noninvasive breast cancer cell lines and HMECs." (PMID 19416474, 2009). "Furthermore, we found that the simultaneous expression of Arf6 and GEP100 in MCF7 human epithelial-like breast cancer cells induced EGF-stimulation-dependent EMT-like changes." (PMID 36408139, 2022). "ARF6 mRNA expression was shown to be up-regulated approximately 5-fold in breast cancer (statistically not significant; p = 02174), 9-fold in lymphoma (statistically significantly p = 0.0309) and 57-fold in EAC (statistically significant; p = 0.0011)." (PMID 35143561, 2022). "A detailed mechanism study revealed that SEV could up-regulate miR-139-5p and down-regulate ARF6, and the decrease in miR-139-5p and increase in ARF6 could at least partly reverse the suppressive effect of SEV on breast cancer." (PMID 34299149, 2021). "Furthermore, in breast cancer cells this lncRNA sponges miR-145, which is a suppressor of the ADP-ribosylation factor 6 (ARF6), key regulator of the process of invasion." (PMID 31003545, 2019). "Components of this pathway are often overexpressed in human breast cancer cells, to be correlated with poor prognosis of the patients, whereas overexpression of the Arf6 pathway did not correlate with the four main molecular classes of human breast tumors." (PMID 29329590, 2018). "Our results suggest that MMTV-PyMT mice, rather than MMTV-Neu mice, are useful to study the Arf6-based mammary tumor malignancies, as a representative model of human breast cancer." (PMID 29329590, 2018). "In breast cancer cells, ligand-activated receptor tyrosine kinases employ GEP100 to activate Arf6, which then recruits AMAP1; and AMAP1 then binds to the mesenchymal-specific protein EPB41L5, which promotes epithelial–mesenchymal transition and focal adhesion dynamics." (PMID 26854204, 2016). "Recent studies including the results from our laboratory showed that Arf6 activation could be induced by EGF and act as a mediator of cell migration and invasion in various types of cancer including breast cancer cells." (PMID 25678857, 2015). "Both the Arf6 and AMAP1 proteins are abnormally overexpressed in highly-invasive breast cancer cell lines, while their expression is minimal in weakly- and non-invasive breast cancer cell lines and also in a primary culture of normal mammary epithelial cells." (PMID 24621372, 2014). "We have shown previously that an Arf6 pathway, in which Arf6 is activated by GEP100 and employs AMAP1 (also called DDEF1 or ASAP1) as its downstream effector, is pivotal for the invasion and metastasis of different breast cancer cells." (PMID 24621372, 2014).
breast carcinoma (continued). "An Arf6 pathway, activated by GEP100 under receptor tyrosine kinases (RTKs) and employs AMAP1 as its effector, is crucial for invasion and metastasis of some breast cancer cells." (PMID 24116160, 2013). "In addition, enhanced expression of Arf6 is observed in breast cancer cells, and GEP100 (also known as BRAG2), an activator for Arf6, is responsible for the invasive activity of MDA-MB-231 breast cancer cells." (PMID 22605996, 2012). "On the other hand, other GEFs, including ARNO and EFA6 which are also known to be robust GEFs against Arf6, are not immediately involved in the invasive activities, while these GEFs are also expressed in breast cancer cells." (PMID 19416474, 2009). "Our analysis on cultured breast cancer cell lines has instead revealed that all of the breast cancer cell lines we examined express comparable levels of Arf6 mRNA, regardless of their invasiveness." (PMID 19416474, 2009). "Moreover, the simultaneous ectopic expression of GEP100 and ARF6 in epithelial-like breast cancer cells resulted in the EGF-dependent conversion from noninvasive to invasive breast cancer cells." (PMID 37834383, 2023). "We have shown that an Arf6 pathway, in which Arf6 is activated by GEP100, a guanine nucleotide exchanging factor (GEF) for Arf-GTPases, and employs AMAP1 (also called DDEF1 or ASAP1) as its downstream effector, is pivotal for the invasion and metastasis of different breast cancer cells." (PMID 24621372, 2014). "Thus, the selective overexpression of the Arf6 protein in highly invasive breast cancer cells appears to be independent of the enhanced transcription of the Arf6 gene, but may be because of its posttranscriptional regulation." (PMID 19416474, 2009). "Protein expression of both Arf6 and AMAP1 is very high in highly-invasive breast cancer cells, but not in weakly- and non-invasive breast cancer cells and normal mammary epithelial cells." (PMID 24116160, 2013). "We have shown that activation of Arf6 by GEP100, but not by other GEFs for Arf6, perturbs formation of E-cadherin-based cell-cell adhesion of breast cancer cells, in which AMAP1 is also essential (will be published elsewhere)." (PMID 24116160, 2013). "Like Arf6, overexpression of the AMAP1 protein in highly invasive breast cancer cells is also independent of the transcriptional upregulation of the AMAP1 gene." (PMID 19416474, 2009). "Protein levels of Arf6 and AMAP1 do not correlate with their mRNA levels in breast cancer cells." (PMID 24621372, 2014). "As for the molecular mechanisms of the Arf6 pathway in invasion, we have shown previously that activation of Arf6 by GEP100, but not by other GEFs, perturbs E-cadherin-based cell-cell adhesion of breast cancer cells and may hence induce their motile phenotypes." (PMID 24621372, 2014). "Besides breast cancer, Arf6 has also been shown to be a component of invadopodia of a melanoma cell line LOX, although it has not been investigated as to whether Arf6 is overexpressed in melanomas." (PMID 19416474, 2009).
pancreatic cancer (30 papers, 2012 to 2025). "In addition, we found that high expression of the Arf6 effector AMAP1 is associated with the fibrosis of pancreatic cancer." (PMID 36408139, 2022). "A related study found that knockdown of ARF6 in pancreatic cancer cell lines strongly enhanced the sensitivity of pancreatic cancer PANC-1 cell lines to RSL3-induced ferroptosis and was accompanied by an increase in the protein expression level of ACSL4." (PMID 37580745, 2023). "Arf6 is frequently overexpressed in several types of cancer, including invasive breast cancer, melanoma and pancreatic cancer and Arf6 activity is driving these tumor cells to become more invasive." (PMID 36494580, 2023). "Further experiments confirmed that abrogation of ARF6 can induce lipid peroxidation and inhibit pancreatic cancer cell growth by regulating ACSL4 protein levels." (PMID 36499358, 2022). "Although ARF6 mRNA expression was shown in this study to be unaltered in breast and pancreatic cancers, an increase in ARF6 protein levels in these cancers has been reported previously, indicating regulation of ARF6 expression at the translational level." (PMID 35143561, 2022). "We have also shown that statins inhibit not only ARF6 activity and invasive potential but also recycling of the immune checkpoint molecule PD-L1 to the plasma membrane in pancreatic cancer cells." (PMID 36408139, 2022). "ADP-ribosylation factor 6 (ARF6) can sensitize gemcitabine-resistance pancreatic cancer cells to RSL3-induced lipid peroxidation by affecting the ACSL4 protein levels." (PMID 33868986, 2021). "Studies have pointed out that ARF6 is highly expressed in the pancreatic cancer cell lines PANC1 and MIA PaCa-2, and its knockdown promotes RSL3-induced ferroptosis." (PMID 34503532, 2021). "Comparing serum levels of WASF2,ARF6,SNORA74A,SNORA25, and CA19‐9 revealed that levels of WASF2 were the most highly correlated with the risk of pancreatic cancer." (PMID 30358104, 2019). "While this study has focused on understanding the Ral-Arf6 crosstalk in WTMEFs and bladder cancer T24 cells (expressing H-Ras), we also detected Ral independent activation of Arf6 in pancreatic cancer MiaPaCa2 cells (expressing K-Ras)." (PMID 27269287, 2016). "Further studies including determination of the activation status of Arf6 will be necessary to reveal the role of Arf6 in the process of pancreatic cancer cell invasion." (PMID 22662237, 2012). "Considering the extensive proliferation of pancreatic cancer, elaborating the relationship between ARF6 and DUSP6 in pancreatic cancer may bring a new strategy for treating this recalcitrant tumor." (PMID 36017891, 2022). "Amongst them, PLD1, EGFR, ST3GAL3 and ARF6 mediate the progression of pancreatic cancer." (PMID 33493138, 2021). "ARF6 is also associated with potentiation of additional growth factor receptors, including epidermal growth factor receptor (EGFR) signaling, and has been associated with beta 1 integrin signaling and pancreatic cancer metastasis to the liver." (PMID 31320995, 2019). "Nude mice were injected with control-RNAi S2-013 cells, and cytoplasmic granules containing IGF2BP3 were evident in the penumbra of each primary pancreatic tumor taken from such a mouse; moreover, ARF6 was enriched near cell membranes in the penumbra of each tumor." (PMID 25216519, 2014). "Similarly to our results, molecular biological studies on ferroptosis in pancreatic cancers revealed that ARF6-silencing increased the expression of ACSL4, which enrich cellular lipid membrane with long PUFAs27, resulting in RLS3-induced ferroptotic cell death of PANC-1 and MIA-Paca249." (PMID 38388563, 2024). "Our results suggest that ARF6 may promote the growth of pancreatic cancer cells through DUSP6." (PMID 36017891, 2022). "ARF6 may contribute to pancreatic cancer development by promoting the Warburg effect." (PMID 36285300, 2022).